RELN (reelin)
Description:
Extracellular matrix serine protease secreted by pioneer neurons that plays a role in layering of neurons in the cerebral cortex and cerebellum by coordinating cell positioning during neurodevelopment. Regulates microtubule function in neurons and neuronal migration. Binding to the extracellular domains of lipoprotein receptors VLDLR and LRP8/APOER2 induces tyrosine phosphorylation of DAB1 and modulation of TAU phosphorylation. Affects migration of sympathetic preganglionic neurons in the spinal cord, where it seems to act as a barrier to neuronal migration. Enzymatic activity is important for the modulation of cell adhesion.
Synonyms: RL; PRO1598; ETL7; LIS2
Tractability: Antibody: its Gene Ontology location is reachable by antibodies, with high confidence; UniProt places it where antibodies can reach, with medium confidence; UniProt predicts a signal peptide or a membrane-spanning region. PROTAC: ubiquitination databases record sites on it; its protein half-life has been measured.
Gene: Protein-coding gene on chromosome 7 (103,471,381 to 103,989,658, reverse strand). Ensembl gene ENSG00000189056.
Subcellular location: Secreted, extracellular space, extracellular matrix
Subcellular location (Human Protein Atlas): Golgi apparatus; Vesicles; Predicted to be secreted
Pathways (Reactome):
Developmental Biology: Reelin signalling pathway
Gene Ontology:
Molecular function: lipoprotein particle receptor binding; receptor ligand activity; serine-type peptidase activity; very-low-density lipoprotein particle receptor binding
Biological process: associative learning; axon guidance; brain development; cell morphogenesis; central nervous system development; cerebral cortex tangential migration; glial cell differentiation; hippocampus development; layer formation in cerebral cortex; long-term memory; modulation of chemical synaptic transmission; neuron migration; NMDA glutamate receptor clustering; positive regulation of dendritic spine morphogenesis; positive regulation of excitatory postsynaptic potential; positive regulation of long-term synaptic potentiation; positive regulation of neuron projection development; positive regulation of phosphatidylinositol 3-kinase/protein kinase B signal transduction; positive regulation of small GTPase mediated signal transduction; positive regulation of synapse maturation; positive regulation of synaptic transmission, glutamatergic; positive regulation of TOR signaling; postsynaptic density assembly; postsynaptic density protein 95 clustering; protein localization to synapse; and 14 more
Cellular component: reelin complex; cytoplasm; dendrite; extracellular matrix; extracellular region; neuron projection; non-collagenous component of interstitial matrix; plasma membrane
Genetic constraint (gnomAD): Loss-of-function variants: 92 observed, 395.92 expected, observed/expected ratio (o/e) 0.23, 90% interval 0.19 to 0.28. The upper end of that interval is the gene's LOEUF score, 0.28, which puts it in group 1 of 6, group 1 being the genes least tolerant of losing a copy. Missense variants: 3,468 observed, 4,231.4 expected, observed/expected ratio (o/e) 0.82, 90% interval 0.8 to 0.84. Synonymous variants: 1,437 observed, 1,506.3 expected, observed/expected ratio (o/e) 0.95, 90% interval 0.91 to 1.
Gene-disease validity (ClinGen):
ClinGen rates the evidence that RELN causes each of these diseases.
lissencephaly with cerebellar hypoplasia (autosomal recessive): Definitive. Lissencephaly with cerebellar hypoplasia (LCH) is a variant form of lissencephaly and involves a heterogeneous group of cortical malformations without severe congenital microcephaly (>-3 SD).
complex neurodevelopmental disorder (autosomal dominant): Disputed. A disorder that involves more than one phenotype associated with the central nervous system, including but not limited to intellectual disability, autism, and seizures (epilepsy).
Homologues: Orthologues: chimpanzee RELN (99% identical), macaque RELN (99% identical), pig RELN (96% identical), dog RELN (96% identical), mouse Reln (95% identical), guinea pig RELN (95% identical), rat Reln (94% identical), tropical clawed frog reln (85% identical).
Diseases named in the same sentence as RELN in open-access papers:
RELN is named in the same sentence as 223 diseases in open-access papers, as found by Europe PMC text mining. Sharing a sentence is not in itself a finding about the gene and the disease. The quoted sentences say what the papers report.
schizophrenia (187 papers, 2006 to 2025). A major psychotic disorder characterized by abnormalities in the perception or expression of reality. "This reduction in reelin expression, coupled with the known association between adolescent SC use and increased risks for mental health problems, including schizophrenia-like episodes, supports the potential link suggested by this study." (PMID 39926699, 2025). "Loss of the reelin protein can prevent neurons from positioning correctly, leading to severe brain defects and neurological disorders such as schizophrenia, autism, bipolar disorder, and major depression in humans." (PMID 40185812, 2025). "Many brain disorders, such as schizophrenia, temporal lobe epilepsy, depression, autism, and neurodegenerative disease, have been associated with dysregulated Reelin expression." (PMID 39339187, 2024). "In humans, the dysregulation of Reelin protein is associated with various neurological disorders, including BD, autism, depression, and schizophrenia." (PMID 38203806, 2024). "In humans, the dysregulation of Reelin protein is associated with various neurological disorders, including schizophrenia, BD, autism, depression, and more." (PMID 38203806, 2024). "A recent genome-wide copy number variation analysis of Japanese schizophrenia patients identified a novel deletion in RELN-encoding Reelin." (PMID 37891846, 2023). "Alongside AD, Reelin is implicated in several neuropsychiatric and neurodegenerative diseases, such as autism, schizophrenia, bipolar disorder, and major depression." (PMID 37461529, 2023). "In a meta-analysis of reelin polymorphism studies, the results proved controversial, as rs7341475 was associated with decreased schizophrenia risk and rs262355 with increased risk." (PMID 38137152, 2023). "The Reelin signalling pathway has been frequently implicated in the pathophysiology of schizophrenia, from both postmortem expression and epigenetic studies in patients." (PMID 36979424, 2023). "This mouse model allowed us to examine sexually dimorphic effects of the RELN-COLBOS variant, a feature that has been described for conditions linked to genetic variation in RELN, including schizophrenia, bipolar disease, autism and Alzheimer’s disease." (PMID 37188781, 2023). "Genetic studies have linked reelin to the pathogenesis of neuropsychiatric diseases, such as schizophrenia, bipolar, and autism spectrum disorders." (PMID 38137152, 2023). "Reelin pathway abnormalities have been linked to various neurological disorders, including schizophrenia and neurodegenerative conditions like Alzheimer’s disease." (PMID 38137152, 2023). "Genetic studies have associated the Reelin gene (RELN) with a number of psychiatric diseases, including schizophrenia, bipolar disorder, and autism spectrum disorder." (PMID 37153634, 2023). "The Apoer2 ligand, Reelin, is implicated in several neuropsychiatric and neurodegenerative diseases, such as autism, schizophrenia, bipolar disorder, major depression, and AD." (PMID 37461529, 2023). "Genetic studies indicate the relationship between the predisposition to develop schizophrenia and the metabolism of reelin, and, at the same time, at least in part, this significantly depends on the gender of the patient (with higher risk for females)." (PMID 38137152, 2023). "Allelic variants of reelin contributed to the endophenotypes of schizophrenia, and positive subjects scored lower in working memory, memory, and executive functioning." (PMID 38137152, 2023). "AA signaling is associated with regulating reelin expression and is reduced in schizophrenia patients, potentially because of dysregulated ARA-dependent upstream signaling." (PMID 36171057, 2022). "In recent years, genome-wide association studies and meta-analyses indicated that rs7341475 and rs262355 genetic polymorphisms in the RELN gene correlated with the onset of schizophrenia." (PMID 35163751, 2022).
schizophrenia (continued). "Because of its function RELN has been associated with diseases such as bipolar disease, schizophrenia and autism." (PMID 36498562, 2022). "In humans, genetic studies have reported that the Reelin (RELN) locus is associated with neuropsychiatric disorders like Schizophrenia, bipolar disorder and autistic spectrum disorder." (PMID 36216926, 2022). "The down-regulated expression of Reelin is clinically associated with neuropsychiatric disorders, such as schizophrenia, autism spectrum disorder (ASD), and Alzheimer’s disease (AD)." (PMID 35163751, 2022). "A de novo copy number variant (CNV) analysis of Japanese schizophrenia patients recently revealed a new pathogenic deletion (12.6 kb) in RELN (RELN-del)." (PMID 35163751, 2022). "Taken together, these findings indicate that changes in Reelin expression and genetic variations are risk factors for schizophrenia." (PMID 35163751, 2022). "The first study on Reelin abnormalities in schizophrenia revealed that RELN mRNA, which encodes Reelin, and Reelin protein expression levels were significantly lower in the postmortem brains of patients with schizophrenia than in non-psychiatric subjects." (PMID 35163751, 2022). "RELN has been consistently linked to schizophrenia based on the gene function and the relationship of its variants with schizophrenia." (PMID 34831111, 2021). "The reelin gene (RELN) has been proposed as a risk gene implicated in several psychiatric disorders, including schizophrenia, depression, and autism spectrum disorders." (PMID 34746116, 2021). "This is supported by evidence of increased levels of methyl donor S-adenosylmethionine (SAM) in the prefrontal cortex of schizophrenia patients and the association of RELN promoter hypermethylation with the RELN protein down-regulation." (PMID 34831111, 2021). "In humans, altered Reelin expression is caused mainly by mutations in the RELN gene or hypermethylation of the RELN promoter, and it has been associated with various brain disorders such as Alzheimer’s disease, schizophrenia and depression." (PMID 33477804, 2021). "Multiple studies have implicated underactive reelin signalin in the etiology of several neuropsychiatric disorders, including schizophrenia, bipolar disorder, autism and major depressive disorder." (PMID 34490028, 2021). "Mutation in RELN, the gene encoding for reelin, have been shown to be associated with autosomal recessive lissencephaly as well as various neuropsychiatric disorders, such as schizophrenia." (PMID 35069108, 2021). "Future studies can facilitate accumulation of sufficient genetic data and clinical phenotypes in humans for elucidation of the molecular mechanisms of schizophrenia caused by a decrease in reelin expression." (PMID 32065683, 2020). "As the results of global behavioral analyses, we found abnormal social novelty in heterozygous Reln‐del mice, indicating that heterozygous Reln‐del mice partially mimicked the Japanese subject with schizophrenia who harbors the same RELN mutation." (PMID 32065683, 2020). "In clinical studies, genetic linkage analyses have implicated RELN polymorphisms in the pathophysiology of neurodevelopmental diseases such as schizophrenia and autism spectrum disorder (ASD)." (PMID 32982694, 2020). "More subtle alterations in Reelin signaling have also been linked to the etiology of various neuropsychiatric disorders such as autism, schizophrenia, bipolar disorder, depression, mental retardation, Alzheimer’s disease and epilepsy." (PMID 32604886, 2020). "For example, mutations in the RELN gene, which encodes Reelin, an extracellular matrix protein involved in neural development and synaptic plasticity, are associated with neurodevelopmental disorders such as schizophrenia and autism spectrum disorder." (PMID 32982694, 2020). "We have identified two novel genetic loci of RELN associated with response to antipsychotic treatment in patients with schizophrenia." (PMID 32082176, 2020).
schizophrenia (continued). "We have further identified a novel exonic deletion of RELN in a patient with schizophrenia, and mice with this RELN mutation exhibit schizophrenia-like behaviors and histological abnormalities." (PMID 32982694, 2020). "As a consequence, the Reelin signaling pathway has been associated with several human brain disorders such as lissencephaly, autism, schizophrenia, bipolar disorder, depression, mental retardation, Alzheimer’s disease and epilepsy." (PMID 32604886, 2020). "This was evidenced by the hypomethylation of CpGs in a specific region of the RELN promoter region, which was associated with the development of cognitive deficits in schizophrenia." (PMID 32764320, 2020). "Evidence has implicated the etiology of schizophrenia with regard to the crucial role of RELN in neurodevelopment." (PMID 32082176, 2020). "Altered reelin signaling has been implicated in the pathogenesis of schizophrenia, bipolar disorder, and autism, all which have been associated with early-life iron deficiency." (PMID 31137889, 2019). "Genetic studies of human patients have demonstrated association between the RELN locus and autism spectrum disorder, schizophrenia, bipolar disorder, and Alzheimer’s disease." (PMID 31607872, 2019). "Genetics studies have also reported that the RELN is associated with multiple neurological diseases including bipolar disorder, schizophrenia, autism spectrum disorder, and Alzheimer’s disease." (PMID 31114610, 2019). "The reelin gene is a susceptibility factor for early-onset psychiatric disorders, such as schizophrenia and autism." (PMID 32116553, 2019). "Human genetic studies suggest that rare RELN variants confer susceptibility to mental disorders such as schizophrenia." (PMID 30022058, 2018). "These mice are used to investigate the role of reelin in the development of psychiatric disorders as mutations in the reelin gene as well as decreased levels of mRNA are associated with autism, schizophrenia and bipolar disorder." (PMID 29941797, 2018). "Our genomic analyses also revealed that the loss of nFGFR1 function in NPCs affected several of the reelin signaling genes, which together with the loss of reelin, denotes the malfunctioning reelin mechanism in the schizophrenia cortex." (PMID 30446636, 2017). "Deficits in Reelin have been documented to be closely associated with mental illness, such as schizophrenia and depression in human subjects; symptoms of mental illness and cognitive impairment in Reelin-knockout mice have also been reported." (PMID 27406263, 2016). "This study demonstrates that schizophrenia patient-derived cells were deficient in reelin-dependent cell motility and focal adhesion formation." (PMID 27602387, 2016). "Our findings indicate possible global defects in cell motility, which provides a platform for testing the roles of specific proteins, such as paxillin or talin, components of focal adhesions, in reelin-associated deficits in schizophrenia." (PMID 27602387, 2016). "Research in the last 20 years, has suggested that abnormal brain RELN expression is a feature that associates with major neuropsychiatric disorders including schizophrenia (SZ), bipolar (BP) disorder, autism, depression, and Alzheimer’s disease." (PMID 27092053, 2016). "Together, these studies elegantly link a disruption of Reelin expression in GABAergic neurons to dendritic spine loss and altered neuronal migration in schizophrenia." (PMID 26839720, 2016). "In humans, genetic studies have shown that the reelin gene (RELN) is associated with a number of psychiatric diseases, including Schizophrenia (SZ), bipolar disorder (BP) and autistic spectrum disorder." (PMID 27803648, 2016). "Decreased cortical Reelin expression has been associated with depression, bipolar disorders and schizophrenia." (PMID 25679528, 2015).
schizophrenia (continued). "While there are a small number of negative studies, the majority of gene expression and genetic association studies implicate altered Reelin signalling in schizophrenia and BD." (PMID 25708817, 2015). "Intriguingly, both the marginal zone and subplate have been shown to highly express some of the genes most significantly linked to neurodevelopmental disorders such as autism and schizophrenia, such as Reelin and TBR1." (PMID 26379512, 2015). "Polymorphisms in RELN associate with the risk of developing schizophrenia in the Han Chinese female population, but this has not been corroborated by Ovadia and Shifman (2011)." (PMID 26696825, 2015). "Reelin (RELN) has been identified as a top candidate gene for schizophrenia in genetic association studies." (PMID 25762938, 2015). "Several disorders, such as autism, schizophrenia, bipolar disorder, major depression and Alzheimer’s disease, have been associated with abnormal levels of reelin in the serum and brain." (PMID 24260534, 2013). "Reelin has also been implicated in pathogenesis of various neuropsychiatric disorders, including schizophrenia, bipolar disorder, lissencephaly, and epilepsy." (PMID 23935565, 2013). "Several reports have implicated reelin signaling in the etiology of neurodevelopmental and psychiatric disorders, including autism, schizophrenia, bipolar disorder, and depression." (PMID 23110844, 2012). "As Reelin, secreted by CR cells, has been implicated in human psychiatric diseases such as schizophrenia, it is particularly important to understand the role of genes involved in the production, migration and differentiation of these cells." (PMID 22421355, 2012). "It is also unclear if reelin, a protein consistently associated with schizophrenia and potentially involved in the mechanism of action of MAM, participates in the neuropathological effects of this compound." (PMID 20421980, 2010). "Reelin was selected for investigation due to its consistent association with schizophrenia and because it can affect neuronal morphology, size and migration." (PMID 20421980, 2010). "In RELN, the strongest signal of association in a GWAS of schizophrenia in Ashkenazi Jews occurred at rs7341475, demonstrating allele frequency differences in female cases and controls (P = 9.8 × 10−5), but not in males (P = 4.7 × 10−1)." (PMID 21104887, 2010). "Thus, potential genes for schizophrenia include genes encoding RELN and proteins implicated in the signaling pathways of RELN." (PMID 39897195, 2025). "However, more research should be carried out to understand the complex mechanisms underlying the relationship between RELN and schizophrenia." (PMID 39897195, 2025). "Additionally, genetic variations impacting the RELN gene expression are associated with an increased risk of schizophrenia development." (PMID 39897195, 2025). "Several heterozygous RELN variants were identified as risk factors for multiple neuropsychiatric and neurodegenerative disorders, such as schizophrenia, bipolar disorders, autism spectrum disorders (ASD), and Alzheimer’s disease in the absence of cortical malformations." (PMID 38980724, 2024). "In addition to neuronal migration, brain development, and adult plasticity, the extracellular matrix protein Reelin has been extensively implicated in human psychiatric disorders such as schizophrenia, bipolar disorder, and autism spectrum disorder." (PMID 37153634, 2023). "Notably, mutations in the reelin-encoding gene, RELN, are linked to schizophrenia in women, autism, and Alzheimer disease, highlighting the importance of this glycoprotein in normal brain physiology." (PMID 37728789, 2023). "A deficiency in Reelin can result in behavioural dysfunction and may contribute to schizophrenia or autism." (PMID 37759530, 2023).